SIX1 (SIX homeobox 1)
Diseases named in the same sentence as SIX1 in open-access papers (continued):
Sharing a sentence is not in itself a finding about the gene and the disease.
cancer (continued). "The most extensively studied Six family member in cancer is Six1, which regulates proliferation, survival, migration and invasion in both a developmental and tumorigenic context." (PMID 20074369, 2010). "However, because Six1 is highly expressed in the developing mammary gland, and because it has been implicated in the expansion of mammary stem cells, targeting Six1 as an anti-cancer therapy may have unwanted side effects in the breast." (PMID 20074369, 2010). "Next, we explored the possibility that Long non-coding RNA (lncRNA) LINC02936/SIX1/CP axis may be a key pathway for inhibiting ferroptosis and promoting cancer progression in EC." (PMID 38385087, 2024). "Because DiPRO1 shares common targets with SIX1 and regulates the myogenic transcriptional program in normal muscle cells, we wondered whether the DiPRO1 and SIX1 gene regulatory network is common to mesenchymal cancer cells." (PMID 39009887, 2024). "Furthermore, DGUOK‐AS1 and SIX1 is stimulated by insulin, a secreted protein related to lipogenesis and cancer, but miR‐145‐5p is inhibited by insulin." (PMID 39258807, 2024). "In adult tissues, the expression of SIX1 is typically low, and any abnormal expression of the SIX1 gene in these tissues could potentially play a role in the development of cancer." (PMID 38250149, 2024). "Thus, we explored that long non-coding RNA (lncRNA) LINC02936/SIX1/CP axis is a key pathway for suppressing ferroptosis and promoting cancer progression in EC." (PMID 38385087, 2024). "Next, we tested whether the DGUOK‐AS1/miR‐145‐5p/SIX1 axis modulates cancer cell proliferation and invasion through lipogenic enzymes." (PMID 39258807, 2024). "Because of the importance of growth factor signals in cancer development and progression, targeting growth factors/SIX1 pathway may be a new approach for cancer therapy." (PMID 39617783, 2024). "Members of the SIX family, especially SIX1, play oncogenic roles in various cancers, which suggests that SIX1 may be a potential therapeutic target in cancer therapy." (PMID 36750914, 2023). "Sine oculis homeobox homolog 1 (SIX1) participates in the development of many cancers." (PMID 36937004, 2023). "SIX1 is overexpressed in many cancers compared to normal tissue." (PMID 36750914, 2023). "Recent studies have shown that SIX1 also promotes cancer progression by promoting glycolysis." (PMID 36937004, 2023). "Besides, SIX1 participates in the rewiring of several cancer signaling pathways, including estrogen, WNT, MAPK, and other pathways, and interacts with cancer stem cells." (PMID 38031089, 2023). "The unique ability to control proliferation in SIX1-overexpressing cells has expanded the utility of MZA for certain types of cancer cells and may find clinical utility." (PMID 34564169, 2021). "Furthermore, our results showed that SIX1 promoted the expression of collagen genes in cancer cells, leading to collagen deposition in the ECM, which subsequently suppressed immune cell infiltration and activation in the TME." (PMID 34782761, 2021). "Therefore, our findings provide evidence explaining how abnormal expression of Six1 in cancer cells affects antitumor immune responses by reshaping the TME." (PMID 34782761, 2021). "Whether reactivated SIX1 uses similar gene regulatory networks to regenerate injured epithelia, akin to the one it uses in cancers, is unclear." (PMID 34513929, 2021). "It correlated with SIX1 mRNA upregulation in cancer tissues." (PMID 33686961, 2021). "Moreover, rescued expression of Col6a1 in Six1−/− MCA205 cancer cells was sufficient to abolish the CD8+ T cell infiltration induced by Six1 deletion." (PMID 34782761, 2021). "Importantly, SIX1 knockdown abolished the ability of miR-489 to regulate the growth of cancer xenografts." (PMID 32258386, 2020).
cancer (continued). "Accumulating studies have showed that SIX1 participates in the occurrence of various human cancers." (PMID 32258386, 2020). "Knockdown of SIX1 effectively downregulated cell growth, glucose uptake and ATP production, suggesting the effect of SIX1 on glucose metabolism was also observed on other types of cancers." (PMID 32201523, 2020). "In BC, SIX1 is highly expressed in half of primary cancers and 90% of cancer metastases." (PMID 33293473, 2020). "Importantly, analysis of TCGA data demonstrated that SIX1 overexpression correlated with poor patient survival, making SIX1 a potential prognostic cancer marker in HNSCC." (PMID 32201523, 2020). "Collectively, these results suggest that SIX1 could play a widespread role in the regulation of SOX2-mediated stem phenotypes in cancer." (PMID 30723235, 2019). "The direct link to SOX2 shown here identifies a novel mechanism by which SIX1 could contribute to self-renewal in cancer stem cells." (PMID 30723235, 2019). "Moreover, the IHC results demonstrated that an increasing expression of Six1 was observed from low malignant tumors to high malignant tumors." (PMID 26161040, 2015). "Importantly, the level of Six1 overexpression is moderate, and well below the level of endogenous Six1 in a number of other cancer cell lines, highlighting that the exogenous expression of Six1 in this system is still within a physiologically relevant range." (PMID 26687066, 2015). "In addition, these results show that increased expression of Six1 predicts poorer outcome of the cancer for the patients compared to those patients with decreased expression of Six1." (PMID 26161040, 2015). "Since Six1 expression is often increased in cancers derived from tissues where it plays an important developmental role, including kidney and muscle, and since Six1 can increase the mammary stem/progenitor pool, we sought to determine if it is involved in the normal development of the mammary gland." (PMID 20074369, 2010). "Targeting growth factors/SIX1 signaling pathway may be beneficial to cancer treatment." (PMID 39617783, 2024). "This suggests that DiPRO1 may regulate neuronal plasticity in cancer through SIX1 targets." (PMID 39009887, 2024). "Finally, we examined the proliferative rate of cancer cells upon alteration of SIX1 expression." (PMID 38031089, 2023). "Inhibition of SIX1 by small interfering RNA may suppress the progression of cancer." (PMID 36750914, 2023). "Moreover, SIX1 participates in the chemoresistance of many cancers." (PMID 35287543, 2022). "Therefore, in SIX1 KO cells miR-7160-induced anti-cancer activity was compromised." (PMID 33686961, 2021). "Consistent with our results, SIX1 can inversely exert its oncogenic effect by activating Wnt/β-catenin signal, which means that there may be a crosstalk between SIX1 and the Wnt/β-catenin pathway in the development of cancer." (PMID 32399910, 2021). "Importantly, miR-7160-induced anti-cancer activity was compromised in SIX1-KO NSCLC cells." (PMID 33686961, 2021). "In addition, there is ample evidence for a role of SIX1 in cancer metastasis and EMT." (PMID 32863962, 2020). "In addition, it has been reported that Six1 up‐regulation induces cancer cell EMT." (PMID 32220051, 2020). "Although SIX1 is a known oncogene overexpressed in many cancers, its expression in CML is unknown." (PMID 30962263, 2019). "All these data suggest that Six1 may participate in oncogenic regulation in many cancers." (PMID 23527134, 2013). "Indeed, we show that Six1 can lead to the expansion of a luminal cancer stem-like cell, and that it does so via its ability to activate both the TGF-β signaling and mitogen activated protein kinase/extracellular signal-regulated kinase (MEK/ERK) signaling pathways." (PMID 22765220, 2012). "Because Six1 causes initiation and metastasis of several types of human cancer, its permanent up-regulation could contribute to the observed increase in FRT cancers in neonatal Gen-treated mice." (PMID 21810550, 2011).
cancer (continued). "Like DGUOK‐AS1, miR‐145‐5p, and SIX1, AIB1 and HBO1 are novel regulators of lipogenic gene expression in cancer cells." (PMID 39258807, 2024). "As DGUOK‐AS1/miR‐145‐5p/SIX1 axis regulates DNL, which plays an important role in modulating cancer cell proliferation and metastasis, we first examined if the DGUOK‐AS1/miR‐145‐5p/SIX1 axis regulates cancer cell proliferation and invasion in vitro." (PMID 39258807, 2024). "By enhancing NF‐κB/p65 pathway in macrophages, SIX1 enhanced the expression of matrix metalloproteinase 9 (MMP-9) and further promoted the invasion of cancer cells." (PMID 36750914, 2023). "Further, SIX1 increases CSC recruit macrophages and stimulate angiogenesis, contributing to the progression of cancer." (PMID 35095892, 2021). "In conclusion, our data demonstrated that SIX1 was overexpressed in HNSCC and promoted cancer progression and glucose uptake by transcriptional upregulation of GLUT3." (PMID 32201523, 2020). "In addition, the expression of Slug and Vimentin, the markers of epithelial-to-mesenchymal transition (EMT) involved in cancer metastasis, was downregulated by miR-489 overexpression or SIX1 knockdown, suggesting that the miR-489/SIX1 axis may play a role in metastasis." (PMID 32258386, 2020). "Emerging evidence has revealed that SIX1 targets ERK and AKT signaling and promotes the malignant behavior of cancer cells." (PMID 33293473, 2020). "Moreover, the success of lipid nanoparticles (LNP)-formulated siRNA targeting VEGF and kinesin spindle protein (KSP) in cancer patients with liver metastasis raised a hope that silencing SIX1 expression using shRNA or miRNA maybe a potential cancer treatment strategy." (PMID 31921695, 2019). "In this context, it should be noted that SIX1 and SIX4 contribute to the regulation of metastasis and EMT in cancer cells." (PMID 30237319, 2018). "The misexpression of homeobox transcription factor genes has also been reported in cancer tissues; for example, HOXA1 and Six1 transform mammary epithelial cells, and Msx1 and Cdx transform myoblasts and intestinal epithelial cells, respectively." (PMID 21600039, 2011). "Alteration of Six1 expression takes place in human breast and Wilms' cancer as well as RMS, indicating its possible contribution in the tumorigenicity of different cancers." (PMID 17008870, 2006). "However, current studies on the synergistic effects of EYA1, SIX1, and DACH1 in promoting angiogenesis predominantly focus on cancer-related aspects, leaving the role of these genes in normal tissue differentiation incompletely understood." (PMID 41329538, 2025). "Conditional deletion of SIX1 in the mouse uterus prevents uterine basal cell formation following DES exposure but does not prevent cancer, indicating that neither SIX1 nor basal cells are required for cancer development in this model." (PMID 37856394, 2023). "EYA enhanced the stemness of cancer stem cells and induced EMT by synergizing with SIX1." (PMID 36750914, 2023). "In addition, miR-186-5p negatively regulated SIX1 and SIX1 was upregulated in DDP resistant cancer cells." (PMID 35444536, 2022). "Cancer cells undergoing EMT can produce the EMT-inducing transcription factor Six1 to promote the metastasis of non-EMT cancer cells." (PMID 36046433, 2021). "Furthermore, the expression of ENO1 and other glycolysis genes also can be regulated by sineoculis homeobox homolog 1 (SIX1), which interact with acetyltransferase 1 (HBO1) and Nuclear receptor coactivator 3 (AIB1) to affect Warburg effect in cancer." (PMID 34671213, 2021). "For more than half of the MES and ADRN TFs (e.g., SIX1, MEOX1, and ZNF536), decreased cumulative survival was observed for two cancer types in particular; KIRP and UCEC, but to a lower extent in other cancers, indicating the influence of these TFs on patient survival in these cancers." (PMID 35201514, 2021). "The mechanisms of SIX regulation of apoptosis is not clear and most investigations have focused on SIX1 in cancer cell lines." (PMID 34490256, 2021).
cancer (continued). "Additionally, as a transcription factor, SIX1 enhances VEGF-C and ZEB1 expression to promote EMT, invasion and metastasis of cancer cells." (PMID 31438963, 2019). "Interestingly, basal cells do not substantially contribute to the cancer phenotype because mouse uteri lacking the oncoprotein Six1 do not develop the basal cell phenotype but still have cancer." (PMID 37856394, 2023). "However, the correlation between SIX1 and cancer patients' prognosis has not yet been systematically evaluated." (PMID 34745930, 2021). "SIX1 could interact with the histone acetyltransferase HBO1 and AIB1 to activate the expression of a series of glycolytic genes 14, which can stimulate the process of cell glycolysis and ultimately promotes cancer progression." (PMID 32863962, 2020). "Two significantly enriched pathways in LUAD and their related DEmRNAs, namely transcriptional misregulation in cancer (TGFBR2, FLI1, ERG and SIX1) and central carbon metabolism (NTRK3 and SLC7A5), were speculated to play key roles in LUAD regulated by DEmiRNAs." (PMID 30761256, 2019). "However, a significant increase in SIX1 and EYA1 was detected in malignant tumor, including FTC (p = 0.011, p = 0.038; respectively), MTC (p = 0.006, p = 0.043; respectively), PTC (p < 0.001, p < 0.001; respectively) and ATC samples (p = 0.002, p < 0.001; respectively)." (PMID 31921695, 2019). "Little or no staining of SIX1 was observed in adjacent non-cancer tissue samples." (PMID 30177858, 2018). "Therefore, we screened TF, proto-oncogenes, tumor suppressor genes, and other TAG from the genes adjacent to aberrant DNA methylation sites, of which multiple known cancer related genes, including MYC, DDR1, MEF2C, NDRG2, SIX1, TNFRSF10B and TSGA10, had HyperM phenomena." (PMID 26046465, 2015). "However, whether SIX1, a major regulator of glycolysis in cancer, can be regulated by O-GlcNAcylation was not clear." (PMID 32863962, 2020). "Although SIX1 is necessary for or mainly involved in some growth factors-mediated promotion of glycolytic gene expression and glycolysis, we do not know whether SIX1 is also important for cancer cell proliferation, invasion, and metastasis regulated by these growth factors." (PMID 39617783, 2024). "To identify cancer cells in the non-basal cell DES clusters, we used expression of Six1, a reliable biomarker of neonatal DES exposure-induced cancer." (PMID 37856394, 2023).
infection (12 papers, 2013 to 2026). The state of being infected such as from the introduction of a foreign agent such as serum, vaccine, antigenic substance or organism. "The specific expression levels of Pax2, Pax8, Eya1, Six1, and Dlx5 in cells from the J1-6d infection scheme were significantly lower than those in the cells infected with NC-shRNA, as shown by semi-quantitative RT-PCR (p < 0.01)." (PMID 34940631, 2021). "This expression pattern differs from that of AVR3 (SIX1), which was found to be expressed early upon infection and green fluorescence can be visualized already one-day post inoculation." (PMID 23596453, 2013). "In support, we detected significantly downregulated expression in the F. oxysporum of key genes involved in infection (SNF1, PL1, Fmk1, and Rho1), colonization (SIX8 and SIX1), pathogenicity (PelD), and hyphal development (FPD1)." (PMID 40078555, 2025). "(C) Images of MEFs reprogrammed with Six1, Atoh1, Pou4f3, and Gfi1 (SAPG) fixed at 14 days post infection (dpi)." (PMID 32602462, 2020). "With the exception of SGE1 and RHR2 all the genes analyzed showed upregulation (twofold or more) during the infection with the HV strain, reaching highest levels for FTF1, SIX1, and RHR1 (more than fivefold increase)." (PMID 25883592, 2015). "In up-regulated genes of head kidney samples, 2 genes respond to infection by D. pseudospathaceum-clone I (HYAL2, PRF1), 3 to clone XII (RGCC, CYP27B1, CCR9) and 6 to the clone mix treatment (ITGA5, SIX1, ATP1B3, MEF2C, MLF1, MYLPF)." (PMID 25254967, 2014). "In line with this, the expression of the virulence effector genes SIX1 and SIX3 at 6 DPI was significantly reduced in ∆kmt6a, further suggesting that this mutant is blocked at an early stage of root infection before reaching the xylem, where SIX genes are fully activated." (PMID 41495884, 2026). "Altogether, the results of this translocation assay indicated that a subset of Fo effectors (Foa2, Foa3, Six8 and Foa4) accumulated inside host cells during infection, and that the putative apoplastic effectors (Six1 and Foa1) and extracellular enzymes did not, and remained extracellular." (PMID 32323328, 2020).
benign tumor (1 paper, 2019). "In comparison with normal tissue, SIX1 and EYA1 kept low expression in benign tumor and no statistic difference was found for either SIX1 or EYA1 between groups." (PMID 31921695, 2019).
myopathy (1 paper, 2025). A disease of the muscle in which the muscle fibers do not function properly. "Collectively, our findings uncover a novel role for the Six1/Eya1 axis in modulating muscle remodeling and fibrosis in TED and provide a foundation for the development of targeted therapies for TED-associated myopathy." (PMID 41227354, 2025). "In our study, we investigated whether Six1 and Eya1, key regulators of myogenesis, modulate the progression of fibroblasts to the myofibroblast phenotype, a critical factor in TED myopathy." (PMID 41227354, 2025).
SIX1 also shares sentences with these, for which no sentence is quoted: esophageal squamous cell carcinoma (4 papers); adenocarcinoma (2); autism (2); Breast Invasive Carcinoma (2); germ cell tumor (2); Hearing impairment (2); Nephropathy (2); open-angle glaucoma (2); 3MC syndrome (1); acute lymphoblastic leukemia (1); acute T-cell leukemia (1); alveolar rhabdomyosarcoma (1); amelogenesis imperfecta (1); and deafness, autosomal dominant 23 (1); atherosclerosis (1); brain cancer (1); branchiootic syndrome 1 (1); Breast Invasive Lobular Carcinoma (1); cerebral infarction (1); cervical tumor (1); chondrosarcoma (1); chronic myeloid leukemia (1); clear cell renal cell carcinoma (1); cleft palate (1); coloboma (1); congenital hypopituitarism (1); DiGeorge syndrome (1); Epstein syndromes (1); fibrosis (1); gastric tumor (1).
A further 40 diseases each share a sentence with SIX1 in 1 paper.